PRPS1 (phosphoribosyl pyrophosphate synthetase 1)
Description:
Catalyzes the synthesis of phosphoribosylpyrophosphate (PRPP) that is essential for nucleotide synthesis.
Synonyms: PRS-I; CMTX5; DFNX1; PPRibP; ARTS; DFN2; PRSI
Tractability: Small molecule: a structure with a bound ligand is known; it has a high-quality binding pocket. PROTAC: ubiquitination databases record sites on it; its protein half-life has been measured.
Target class: Enzyme; Transferase
Gene: Protein-coding gene on chromosome X (107,628,428 to 107,651,993, forward strand). Ensembl gene ENSG00000147224.
Subcellular location (Human Protein Atlas): Vesicles
Pathways (Reactome):
Metabolism: 5-Phosphoribose 1-diphosphate biosynthesis
Gene Ontology:
Molecular function: ATP binding; identical protein binding; protein binding; protein homodimerization activity; ribose phosphate diphosphokinase activity; magnesium ion binding
Biological process: hypoxanthine biosynthetic process; nervous system development; purine nucleobase metabolic process; purine nucleotide biosynthetic process; urate biosynthetic process; 5-phosphoribose 1-diphosphate biosynthetic process; protein hexamerization; pyrimidine nucleotide biosynthetic process; male gonad development; nucleotide biosynthetic process; ribonucleoside monophosphate biosynthetic process
Cellular component: cytoplasm; cytosol; ribose phosphate diphosphokinase complex
Gene-disease validity (ClinGen):
ClinGen rates the evidence that PRPS1 causes each of these diseases.
PRPS1 deficiency disorder (X-linked): Definitive. A peripheral neuropathy that is characterized by variants in PRPS1, which causes decreased or impaired function of the PRPS1 enzyme, and presents as a range of peripheral neuropathies that can include features of Charcot-Marie Tooth syndrome, Arts syndrome, or nonsyndromic hearing loss.
phosphoribosylpyrophosphate synthetase superactivity (X-linked): Limited.
Homologues: Orthologues: macaque PRPS1 (100% identical), mouse Prps1 (100% identical), pig PRPS1 (100% identical), tropical clawed frog prps1 (97% identical), zebrafish prps1a (97% identical), zebrafish prps1b (97% identical), Drosophila melanogaster Prps (88% identical), Caenorhabditis elegans R151.2 (81% identical). Paralogues in human: PRPS2 (95% identical), PRPS1L1 (94% identical), PRPSAP2 (49% identical), PRPSAP1 (49% identical).
Diseases named in the same sentence as PRPS1 in open-access papers:
PRPS1 is named in the same sentence as 89 diseases in open-access papers, as found by Europe PMC text mining. Sharing a sentence is not in itself a finding about the gene and the disease. The quoted sentences say what the papers report.
Arts syndrome (25 papers, 2014 to 2025). Lethal ataxia with deafness and optic atrophy (also known as Arts syndrome) is characterized by intellectual deficit, early-onset hypotonia, ataxia, delayed motor development, hearing impairment and loss of vision due to optic atrophy. "PRPS1 mutations have been identified as the causative factor of Arts syndrome, which is characterized by cognitive impairment, hearing impairment, optic atrophy, early-onset hypotonia, ataxia and delayed motor development." (PMID 37308732, 2024). "PRPS1 gene mutations have been implicated in several diseases, such as Arts syndrome, an X-chromosome-linked genetic disorder distinguished by cognitive impairment, delayed motor development and hearing impairment." (PMID 37308732, 2024). "Severe PRPS1 deficiency, also known as Arts syndrome (OMIM #301835), is an X‐linked condition characterized by congenital sensorineural hearing loss, optic atrophy, developmental delays, ataxia, hypotonia, and recurrent infections." (PMID 37927483, 2023). "Female carriers of pathogenic PRPS1 variants range from asymptomatic to varying degrees of isolated hearing loss to a more severe CMTX5 or Arts syndrome phenotype, with significant phenotypic variability." (PMID 37927483, 2023). "Clinical experience appears to show the benefit of SAMe and NR in individuals with a severe PRPS1 deficiency phenotype, or Arts syndrome, and we feel that these therapies in Arts syndrome patients should be considered." (PMID 37927483, 2023). "It is worth noting that mutations in p.S16P and p.R214W have also been associated with hearing loss, emphasizing the importance of PRPS1 in overlapping human diseases, i.e., syndromic hearing loss and Arts syndrome (p.Q133P)." (PMID 35741038, 2022). "ATP6AP2 mutations are found in X-linked ID with Parkinsonism and spasticity, and PRPS1 mutations in Arts syndrome, X-linked recessive Charcot-Marie-Tooth disease 5 and X-linked non-syndromic hearing loss." (PMID 36551904, 2022). "The first two-named also cause gain-of-function, i.e., PRPS1 superactivity whereas p.Q133P and p.L152P give rise to both Arts syndrome and congenital hearing loss." (PMID 35741038, 2022). "Reduced activity in PRPS1 is associated with neurological disorders, such as Arts syndrome, Charcot-Marie-Tooth disease type 5 (CMTX5), X-linked syndromic/nonsyndromic sensorineural deafness (DFN2/DFNX2) and retinal dystrophy." (PMID 35741038, 2022). "Among the three human orthologs, missense mutations of PRPS1 are found in a number of rare neurological disorders such as Arts syndrome." (PMID 32650483, 2020). "Two mutant alleles carrying PRPS1 mutations identified from Arts syndrome, Q133P and R196W, were engineered in flies." (PMID 32650483, 2020). "The spectrum of X-linked neurological disorders that are associated with decreased PRPS1 function includes Arts syndrome, Charcot-Marie-Tooth disease 5 (CMTX5), nonsyndromic sensorineural deafness 2 (DFN2), and more recently retinal dystrophy." (PMID 32650483, 2020). "PRPS1 is linked to three different phenotypes, always associated with hearing loss: CMTX5, DFNX1 and Arts syndrome." (PMID 31393079, 2019). "PRPS1 loss-of-function mutations have been previously related to disease phenotypes like Arts Syndrome, diabetes insipidus or hearing loss." (PMID 30379953, 2018). "This resembles the features of more severe human PRPS1 mutations such as Arts Syndrome that have increased phenotypic severity and premature death." (PMID 27425195, 2016). "More severe reductions of PRPS1 activity are associated with Arts Syndrome where patients have not only hearing impairment, optic atrophy, and peripheral neuropathy, but also central neuropathy and a deficient immune response (MIM 301835)." (PMID 27425195, 2016). "Human patients with Arts Syndrome, the disease associated with severe mutations in the PRPS1 gene, experience recurrent infections." (PMID 27425195, 2016).
Arts syndrome (continued). "Two loss-of-function PRPS1 mutations have been associated with Arts syndrome, namely, c.398A>C (p.Q133P) and c.455T>C (p.L152P)." (PMID 26089585, 2015). "The predicted structural effects of the p.Gln277Pro mutation fall in between those of the CMTX5 and Arts syndrome PRPS1 mutations, thus explaining the CMTX/Arts syndrome overlapping phenotype in the male index patient II-2." (PMID 24528855, 2014). "Furthermore, Arts-syndrome-associated PRPS1 R196W mutant exhibits decreased PRPS1 O-GlcNAcylation and activity." (PMID 37308732, 2024). "Arts syndrome, or severe PRPS1 deficiency, is an X‐linked condition characterized by congenital sensorineural hearing loss, optic atrophy, developmental delays, ataxia, hypotonia, and recurrent infections that can cause progressive clinical decline, often resulting in death before 5 years of age." (PMID 37927483, 2023). "The mutation p.V142L causes an intermediate phenotytpe of PRPS1 superactivity and Arts syndrome." (PMID 35741038, 2022). "However, a marked reduction in PRPS1 activity in erythrocytes was recorded in this patient, emphasizing the necessity of testing for all parameters associated with Arts syndrome." (PMID 35741038, 2022). "A male subject, aged 36, p.Q277P (c.830A > C), displayed overlapping features of CMTX5 and Arts syndrome, prelingual hearing loss, recurrent severe infections and progressive visual loss due to optic atrophy, as well as undetectable PRPS1 activity in erythrocytes." (PMID 35741038, 2022). "In conclusion, we present a novel PRPS1 loss-of-function variant in a patient with some clinical features of Arts syndrome, but lacking a major attribute, hearing loss, which is congenital/early-onset in all other reported Arts syndrome patients." (PMID 33294372, 2020). "Interestingly, similar neurological symptoms are observed in patients affected by Arts syndrome, a severe disease in which a missense mutation completely inactivates PRPS1." (PMID 29375373, 2017). "Mutations in PRPS1 are normally found in the more severe Arts syndrome, Charcot-Marie Tooth, and nonsyndromic sensorineural deafness, so if mutations in this gene had only been identified in one family, this may have been disregarded as the pathogenic cause of disease." (PMID 30915099, 2019). "We found that Arts-syndrome-associated PRPS1 R196W mutation decreased OGT binding, PRPS1 O-GlcNAcylation and activity." (PMID 37308732, 2024). "The mutations of PRPS1 lead to some neurodevelopmental diseases too, including PRS-I superactivity, Charcot-Marie-Tooth disease-5 (CMTX5, or Rosenberg-Chutorian syndrome), Arts syndrome, and X-linked nonsyndromic sensorineural deafness (DFN2)." (PMID 36743290, 2022). "Three clinical phenotypes are associated with loss-of-function PRPS1 variants and decreased PRPS activity: Arts syndrome (OMIM: 301835), Charcot-Marie-Tooth disease type 5 (CMTX5, OMIM: 311070), and nonsyndromic X-linked deafness (DFN2, OMIM: 304500)." (PMID 33294372, 2020). "In Arts syndrome, a disease with a severe reduction of PRPS1 activity, recurrent infection is characteristic and often causes early death." (PMID 27425195, 2016). "Until recently, 15 PRPS1 mutations have been identified: 2 in Arts syndrome, 2 in CMTX5 syndrome, 7 in PRPS1 superactivity, and 4 in DFNX-2." (PMID 26089585, 2015). "A new family with a novel PRPS1 missense mutation, c.830A>C (p.Q277P), has been reported with features resembling both CMTX5 and Arts syndrome." (PMID 26089585, 2015). "When comparing the protein structural effects of all known PRPS1 mutations and their relations to PRPS1-phenotypic clusters, the p.Gln277Pro (Q277P) mutation falls in between CMTX5 and Arts syndrome PRPS1 mutations." (PMID 24528855, 2014). "Our findings indicate that CMTX5, Arts syndrome and DFN2 are phenotypic clusters on a continuous intraindividual and intrafamilial spectrum of PRPS1-disease." (PMID 24528855, 2014).
Arts syndrome (continued). "Like other Arts syndrome mutations (and in contrast to CMTX5 PRPS1 mutations), it is predicted to disrupt the local PRS-I structure." (PMID 24528855, 2014). "Arts syndrome is associated with missense mutations causing remarkable loss of PRPS1 activity (absent in erythrocytes and up to 1/10 of normal in fibroblasts) and is characterized by more severe symptoms." (PMID 37512494, 2023). "To date, 34 missense variants have been reported in HGMD leading to four distinct syndromes: PRPS1 superactivity (OMIM#300661), X-linked Charcot-Marie-Tooth disease-5 (CMTX5: OMIM#311070), Arts syndrome (OMIM#301835), and isolated X-linked sensorineural deafness (DFNX1: OMIM#304500)." (PMID 31906484, 2020). "Thus, the variants in the PRPS1 gene can lead to different conditions due to hypoactivity, such as X‐linked CMT type 5 (CMTX5), Arts syndrome and X‐linked deafness (DFNX1); or PRS superactivity, which can induce gout." (PMID 31338985, 2019). "Phosphoribosyl pyrophosphate synthetase-1 (PRPS1) is a key enzyme in nucleotide biosynthesis, and mutations in PRPS1 are found in several human diseases including nonsyndromic sensorineural deafness, Charcot-Marie-Tooth disease-5, and Arts Syndrome." (PMID 27425195, 2016). "Mutations in the PRPS1 can either result in a gain of function with increased expression, PRPS1 superactivity, or result in a loss of function with a decreased expression, DFN-2, CMTX5, and Arts syndrome." (PMID 26089585, 2015). "Here we report a novel mutation in PRPS1 leading to PRS-I deficiency in three-females from a family with a phenotype consisting of OA followed by RP in all cases, plus neurological features overlapping CMTX5 and Arts syndrome with variable presentation in the proband (IV:3) and her mother (III:2)." (PMID 25491489, 2014). "Missense variants in PRPS1 can result in increased or decreased PRS-I activity, leading to disorders such as PRS-I superactivity, DFNX1, CMTX5, and Arts syndrome." (PMID 40677922, 2025). "In summary, there are several manifestations, e.g., PRPS1 superactivity and recurrent infections, which can be traced back to the p.V142L mutation resulting in intermediate phenotypes lacking the severity of those associated with Arts syndrome (p.Q133P or p.L152P)." (PMID 35741038, 2022). "Gain-of-function in hPRPS1 causes PRPS1 superactivity via the alteration of allosteric sites I and II, affecting either the trimer or the dimer interfaces, whereas the loss-of-function mutations in hPRPS1 result in the following neurological disorders: Arts syndrome, CMTX5 and DFNX1/DFN2." (PMID 35741038, 2022). "So far, cerebral MRI abnormalities have been observed neither in CMTX5 nor in Arts syndrome, yet such abnormalities are likely given the wide range of clinical central nervous abnormalities in PRPS1-disorders, in particular in Arts syndrome." (PMID 24528855, 2014). "However, unlike the other Arts syndrome mutations and in line with the CMTX PRPS1 mutations, it is not predicted to disturb the allosteric site II or to affect the dimer interface." (PMID 24528855, 2014).
hearing loss (19 papers, 2014 to 2025). "A common symptom associated with most PRPS1 mutations is hearing impairment (either nonsyndromic or syndromic hearing loss)." (PMID 37512494, 2023). "PRPS1 is found on many commercially available genetic panels for hearing loss, intellectual disability, and optic atrophy; however, review of individual panels is recommended." (PMID 37927483, 2023). "The patient's mother, who had childhood onset hearing loss, was found to be a carrier for the PRPS1 c.383A>T variant." (PMID 37927483, 2023). "A further hemizygous mutation c.82G > C (p.G28R) has been reported in a Japanese male with CMTX5 with typical clinical features, i.e., neuropathy, optic atrophy, and hearing loss, but with only mild loss of PRPS1 activity in erythrocytes." (PMID 35741038, 2022). "Human PRPS1-related diseases can be characterized by a continuous spectrum of features spanning neuropathies, hearing loss, optic atrophy, ataxia, cognitive impairment, and recurrent upper-respiratory infections." (PMID 35741038, 2022). "Regardless of their effect on enzymatic activity, a common symptom associated with most PRPS1 mutations is hearing impairment (either nonsyndromic or syndromic hearing loss)." (PMID 32650483, 2020). "A moderate reduction of PRPS1 activity is associated with X-linked Charcot-Marie-Tooth where patients have hearing impairment, together with optic atrophy and peripheral neuropathy (CMTX5, MIM 311070)." (PMID 27425195, 2016). "Since hearing impairment is a common symptom shared by several PRPS1-associated diseases, we examined neuromast hair cell innervation as a potential source of pathology." (PMID 27425195, 2016). "Taken together, these findings suggest a continuous spectrum of PRPS1 disease features, where hearing loss, peripheral neuropathy, optic atrophy, ataxia, cognitive deficits and recurrent infections are central, yet variable phenotypic features." (PMID 24528855, 2014). "Moderate to mild PRPS1 deficiency is associated with hearing loss with later onset ataxia and optic neuropathy, also known as Charcot Marie Tooth Disease X linked 5 (CMTX5, OMIM #311070), or isolated hearing loss, also known as deafness X‐linked 1 (DFNX1, OMIM # 304500), respectively." (PMID 37927483, 2023). "Hearing impairment and ataxia are characteristics of PRPS1-associated diseases in humans." (PMID 27425195, 2016). "Using whole exome sequencing (WES), we identified a novel loss-of-function mutation in PRPS1 leading to enzyme deficiency in three females with optic atrophy (OA), retinitis pigmentosa (RP), ataxia, peripheral neuropathy and hearing loss with variable presentation." (PMID 25491489, 2014). "In conclusion, PRPS1 may be considered as an example of a human gene in which activating and inactivating mutations cause distinct hereditary disorders with overlapping neurological abnormalities, such as hearing impairment." (PMID 37512494, 2023). "Progressive hearing loss is an isolated feature in DFNX1 patients, presenting half-normal PRPS1 activity in the erythrocytes and fibroblasts." (PMID 37512494, 2023). "X‐linked hearing loss accounts for <1%–2% of nonsyndromic hearing loss overall and PRPS1 variants were not identified in large cohorts of patients with nonsyndromic hearing loss." (PMID 37927483, 2023). "A novel missense variant with an amino acid change p.M115V (c.343A > G) was identified in a 12-year-old Italian male who had post-lingual bilateral hearing impairment, which worsened upon ageing; PRPS1 enzyme activity in erythrocytes was reduced to less than 10% of the control." (PMID 35741038, 2022). "The incidence of hearing loss related to PRPS1 is not well characterized." (PMID 37927483, 2023). "His sister had reduced PRPS1 activity in addition to prelingual nonsyndromic hearing loss and deafness (DFN2/DFNX1), whereas their mother had normal PRPS1 activity and no hearing loss." (PMID 35741038, 2022).
Ataxia (12 papers, 2014 to 2024). Ataxia refers to impaired coordination of voluntary muscle movement. "Abnormally high expression of PRPS1 can cause many diseases, including hearing loss, hypotonia, and ataxia, in addition to being associated with neuroblastoma." (PMID 31443513, 2019). "PRPPS (Prps1, Prps1l1, Prps2) was previously reported to be affected by amino acid depletion, while mutations in Prps1 have been associated with hyperuricemia, hyperuricosuria, hypotonia, and ataxia and gain-of-function mutation results in PRS-1 superactivity." (PMID 31285465, 2019). "The OPCA pattern was identified as MSA-C in a few dominant ataxias (SCA1-3, SCA7, SCA34, SCA36, DRPLA), two recessive ataxias (BNS and SCAR7) and the X-linked ataxia associated with the PRPS1 gene mutation." (PMID 35202200, 2022).
optic atrophy (12 papers, 2014 to 2024). A disorder characterized by loss of optic nerve fibers. "Patients who developed polyneuropathy associated to sensorineural deafness and optic atrophy during childhood should be assessed for PRPS1." (PMID 31338985, 2019). "An earlier report already indicated that some subjects can present with an only incomplete presentation of a PRPS1 disease cluster (e.g. absence of optic atrophy in CMTX5 subjects)." (PMID 24528855, 2014).